SRF (serum response factor)
Diseases named in the same sentence as SRF in open-access papers (continued):
Sharing a sentence is not in itself a finding about the gene and the disease.
infection (continued). "The lower efficiency of transfection compared to infection, together with the ability of dsRed to fill the whole neuron with red fluorescence, allowed a clear visualization of the impact of the chronic manipulation (7 days) of SRF activity on the morphology of individual neurons." (PMID 26638868, 2015). "Like both SRF and IL-2, the transcription factor IRF4 is dispensable for initial CD8+ T-cell activation and proliferation during infection, but necessary for sustained expansion and SLEC proliferation." (PMID 39261466, 2024). "We next used the co-transfer approach to investigate the contributions of the two families of signal-regulated SRF co-factors, the TCFs and the MRTFs33, to the CD8+ T-cell response during LM-OVA infection." (PMID 39261466, 2024). "Specifically, in cluster 2 with the highest viral load, only three genes including PUM1 (Pumilio homolog; BMSK0008893), PLX-4 (plexin homolog; BMSK0010793), and blistered (bs) (ortholog of serum response factor; BMSK0013093) were significantly up-regulated by BmNPV infection." (PMID 41325423, 2025). "Further studies have indicated that SRF utilizes MKL1/2 to fulfill steady-state cellular functions, including cytoskeletal organization, and utilizes ELK4 to facilitate acute responses to external infection." (PMID 41472164, 2025). "Interestingly, however, the first vhs-dependent gene significantly downregulated in 4sU-RNA of WT infection at 2–3 h p.i. was the ETS transcription factor ELK3, one of three ternary complex factors (TCFs) that act as cofactors of serum response factor (SRF)." (PMID 33148793, 2021). "HOMER analysis detected the enrichment of motifs in the promoters of differentially expressed genes for NF-κB and the MAPK-activated transcription factor SRF, indicating that these pathways are likely upstream of AP-1/ATF-2/NFAT-mediated gene expression, as detected by RNAseq at 6 h post-infection." (PMID 29868516, 2018). "I conclude that SRF utilizes MKL1/2 to fulfill steady state cellular functions, including cytoskeletal organization, and utilizes ELK4 to facilitate acute responses to external infection." (PMID 24758171, 2014). "These master regulators include EGR1, FOS, SRF, and SP1, and could be interesting targets for future studies, since they could switch on several pathways targeting the genes that are important to the successful alleviation of HPAI infection." (PMID 35205087, 2022). "The overall view of the genome-wide locations of SRF, MKL1 and ELK4 has been constructed and the results suggest that SRF utilizes MKL1 to fulfill steady state cellular functions, including cytoskeletal organization, and utilizes ELK4 to facilitate acute responses to external infection." (PMID 24758171, 2014). "RH-ERP and GT1 also differ in the modulation of certain host processes; a serum response factor (SRF) reporter cell line is activated more by RH-ERP compared to GT1, and transcript levels of early growth response factor 2 (EGR2), a SRF target gene, are higher upon RH-ERP infection compared to GT1." (PMID 23837824, 2013). "This is supported by the fact that no SRF target genes were induced by infection with EPEC Δtir." (PMID 21490959, 2011).
heart disease (7 papers, 2012 to 2025). "Although multiple TRIM family proteins have been shown to be involved in various cardiac diseases, the roles they play and the extent of their association with SRF remain to be explored." (PMID 35681202, 2022). "Taken together, these findings indicate that SRF plays a critical role in regulating cardiac health and that our model can be used to study heart disease mechanisms." (PMID 40164849, 2025). "Therefore, tightly regulating SRF expression in the heart is crucial in preventing the onset of cardiac diseases and mitigating mitochondrial dysfunction, emphasizing its potential as a therapeutic target for mitigating cardiac aging." (PMID 40164849, 2025). "Do all cardiac diseases exhibited disrupted SRF or SRF-related molecules?" (PMID 35681202, 2022). "The phosphorylated state of SRF plays a crucial regulatory role in cardiac diseases." (PMID 35681202, 2022). "In light of the involvement of SRF in adverse cardiac remodeling, it has been of interest to explore the potential contributions of MYOCD family members, as SRF coactivators, to heart disease." (PMID 22666593, 2012). "The role of SRF in cardiac diseases is not always detrimental." (PMID 35681202, 2022).
cardiovascular diseases (5 papers, 2021 to 2023). "Alteration of SRF activity contributes to the disruption of cardiovascular homeostasis and is associated with a wide range of cardiovascular diseases." (PMID 34381779, 2021). "However, what roles does SRF play in cardiovascular diseases?" (PMID 35681202, 2022). "Enhanced ROCK activity on fibroblasts in cardiovascular diseases is responsible for the de novo expression of a pro-fibrotic gene program through the TGF-β, MRTF/serum response factor (SRF) and YAP/TAZ pathways." (PMID 34209333, 2021). "Serum response factor (SRF) controls gene transcription in vascular smooth muscle cells (VSMCs) and regulates VSMC phenotypic switch from a contractile to a synthetic state, which plays a key role in the pathogenesis of cardiovascular diseases (CVD)." (PMID 37292911, 2023).
myopathy (4 papers, 2008 to 2023). A disease of the muscle in which the muscle fibers do not function properly. "In this model, before injury, muscle lacking SRF presented a myopathy characterized by a drastic myofiber hypotrophy and impaired maturation." (PMID 19079548, 2008).
neurological disorders (4 papers, 2014 to 2023). "In contrast to the physiological function of the SRF cofactor MKL/MRTF, the dysfunction of MKL/MRTF might be involved in the etiology of neurological disorders." (PMID 34795561, 2021).
neurodegenerative disease (3 papers, 2019 to 2025). A disorder of the central nervous system characterized by gradual and progressive loss of neural tissue and neurologic function. "Importantly, in the setting of both excitotoxicity and neurodegenerative disease these Srf-deficient reactive astrocytes provide significant neuroprotection and thus making astrocytic SRF a potential therapeutic target." (PMID 38289036, 2024). "Taken together, our results reveal SRF as a critical regulator of neuroprotective reactive astrogliosis in the context of brain injury and neurodegenerative disease." (PMID 38289036, 2024). "Taken together, these findings establish SRF as a key molecular switch for the generation of reactive astrocytes with neuroprotective functions that attenuate neuronal injury in the setting of neurodegenerative diseases." (PMID 38289036, 2024). "Nevertheless, further investigation is needed to identify the roles of CRAG-mediated SRF activation in neuronal development and the pathogenesis of neurodegenerative diseases." (PMID 31882856, 2019).
metabolic disease (2 papers, 2020 to 2023). A congenital disorder (due to inherited enzyme abnormality) or acquired (due to failure of a metabolically important organ) disorder resulting from an abnormal metabolic process. "One candidate gene was methyltransferase-like 8 (METTL8), which has been associated with metabolic disease in humans, body weight in chicken and myogenic differentiation by influencing myogenic gene expression (SRF and MEF2) in mouse." (PMID 33370292, 2020).
neurodevelopmental disorder (2 papers, 2022 to 2023). A behavioral and cognitive disorder with onset during the developmental period that involves impaired or aberrant development of intellectual, motor, or social functions. "Altogether, structural and functional alterations of dendritic spines observed in SRF-depleted neurons implicate excitatory synapses as crucial substrates of pathogenesis in different neurodevelopmental disorders." (PMID 35505150, 2022). "The presented findings implicate developmental SRF activity in the pathogenesis of neurodevelopmental disorders." (PMID 35505150, 2022).
connective tissue disorder (1 paper, 2014). A disease involving the connective tissue. "Thus, the SRF-dependent/SAP-independent signature implicated a function of these genes in cellular movement and the linked diseases included connective tissue disorders, inflammatory disease and skeletal and muscle disorders, which are the main features known to be regulated by SRF/Mkl1 interaction." (PMID 24495796, 2014).
gastrointestinal tumors (1 paper, 2013). "In the present study, we found that part of GFP(+) stromal cells were also αSMA(+) or SRF(+) myofibroblasts, and some of them were CD45(+) hematopoietic cells in mouse H. felis/NMU-induced gastrointestinal tumors." (PMID 24260263, 2013).
SRF also shares sentences with these, for which no sentence is quoted: hypertrophy (3 papers); metastatic melanoma (3); cerebral amyloid angiopathy (2); colitis (2); colon cancer (2); familial exudative vitreoretinopathies (2); glioblastoma (2); hematological malignancies (2); myopia (2); type 2 diabetes (2); acute myeloid leukemia (1); adolescent idiopathic scoliosis (1); alveolar rhabdomyosarcoma (1); amyotrophic lateral sclerosis (1); anaphylaxis (1); atopic dermatitis (1); bacterial infection (1); basal cell carcinoma (1); bipolar disorder (1); Brain atrophy (1); breast tumor (1); cervical cancer (1); chondroid syringomas (1); colon adenocarcinoma (1); Diabetes Mellitus Type 1 (1); Duchenne muscular dystrophy (1); embryonic carcinoma (1); esophageal cancer (1); head and neck squamous cell carcinoma (1); Helicobacter pylori (1).
A further 35 diseases each share a sentence with SRF in 1 paper.